MIR3142HG (MIR3142 host gene)
Gene: Long non-coding RNA gene on chromosome 5 (160,438,594 to 160,600,965, forward strand). Ensembl gene ENSG00000253522.
Gene Ontology:
Biological process: miRNA-mediated post-transcriptional gene silencing
Cellular component: RISC complex
Diseases named in the same sentence as MIR3142HG in open-access papers:
MIR3142HG is named in the same sentence as 3 diseases in open-access papers, as found by Europe PMC text mining. Sharing a sentence is not in itself a finding about the gene and the disease. The quoted sentences say what the papers report.
cancer (1 paper, 2023). A tumor composed of atypical neoplastic, often pleomorphic cells that invade other tissues. "The role of MIR3142HG in cancer progression is currently controversial." (PMID 37048115, 2023).
infection (1 paper, 2022). The state of being infected such as from the introduction of a foreign agent such as serum, vaccine, antigenic substance or organism. "Of note, three of the four genes that were significantly regulated in all investigated conditions showed lessened induction upon concomitant infection and Smh1 expression (IL-1β, GLIS3, and MIR3142HG), while down-regulation of the fourth factor (RGS4) is accentuated by Smh1 expression." (PMID 36411449, 2022).
tumor (1 paper, 2021). "AC023310.4, AC091729.1, LINC01564, and MIR3142HG were expressed at higher levels in tumor samples compared to adjacent non-tumor tissues." (PMID 35127708, 2021).